CDC25B (cell division cycle 25B)
Diseases named in the same sentence as CDC25B in open-access papers (continued):
Sharing a sentence is not in itself a finding about the gene and the disease.
paraganglioma (2 papers, 2021 to 2025). A benign or malignant neoplasm arising from paraganglia located along the sympathetic or parasympathetic nerves. "High CDC25B expression levels might also beneficial to the overall survivals of pheochromocytoma and paraganglioma (PCPG) and testicular cancer (TGCT) patients." (PMID 33745968, 2021). "Distinct from CDC25A and CDC25B, the methylation level of CDC25C decreased in most tumor tissues, including KIRP, LUSC, PRAD, UCEC, LIHC, BLCA, LUAD, and pheochromocytoma and paraganglioma (PCPG)." (PMID 40216745, 2025).
thyroid carcinoma (2 papers, 2002 to 2025). "It is thus suggested that cdc25B plays a crucial role in the progression of thyroid carcinoma in the early stage, as well as in the tumorigenesis of follicular cells of the thyroid, rather than merely in tumour cell proliferation." (PMID 12085185, 2002). "The significant reduction of cdc25B expression in dedifferentiated thyroid carcinoma has prompted researchers to investigate its prognostic value." (PMID 12085185, 2002). "Furthermore, the cdc25B expression level significantly decreased with the dedifferentiation of thyroid carcinoma." (PMID 12085185, 2002).
viral infections (2 papers, 2023 to 2024). "Existing studies have shown that STMN1 plays an important role in viruses infection, and low expression of STMN1 inhibits dengue viruses replication; In addition, miR-760-3p regulates decreased expression of MEF2B and CDC25B." (PMID 38178220, 2024). "For example, Cell Division Cycle 25B (Cdc25b), a key factor for virus replication, showed DRE in viral infections only but not in bacterial infections." (PMID 37081881, 2023).
vulvar squamous cell carcinoma (2 papers, 2010 to 2021). An invasive squamous cell carcinoma arising from the vulva. "In vulvar squamous cell carcinoma, overexpression of CDC25B, CDC25C, and phosphor-CDC25C is linked to malignant features and aggressive cancer phenotypes." (PMID 33925358, 2021). "The aims of our study were to determine expression statuses of CDC25A, CDC25B and CDC25C in a large series of vulvar squamous cell carcinomas to shed light on their roles in the pathogenesis of this cancer type and to clarify their potential prognostic values." (PMID 20500813, 2010).
Alzheimer disease (1 paper, 2022). A progressive, neurodegenerative disease characterized by loss of function and death of nerve cells in several areas of the brain leading to loss of cognitive function such as memory and language. "In Alzheimer’s disease, CDC25B activity increases the abnormal expression of Cdc2/cyclin B, resulting in various downstream indicators of mitotic events and eventually leading to neurodegeneration." (PMID 35497000, 2022).
bipolar disorder (1 paper, 2018). A disorder of the brain that causes unusual shifts in mood, energy, activity levels and the ability to carry out day-to-day tasks. "As a result of analysis by DeSeq 2.0, NRAS and CDC25B targeted genes happened to be DE in the frontal cortex of schizophrenia-vs-controls and bipolar-disorder–vs-controls groups, respectively when considering a significance threshold of adjusted P value ≤ 0.1 after correcting for multiple testing." (PMID 29745862, 2018). "Further schizophrenia and bipolar disorder patients have shown higher expression of two different targeted genes: NRAS and CDC25B, respectively, in the frontal cortex than controls." (PMID 29745862, 2018). "We identified four rSNP-targeted genes that showed differential expression between patient and control groups depending on brain region: NRAS—in schizophrenia cohort, CDC25B, DDX21 and NUCKS1—in bipolar disorder cohort." (PMID 29745862, 2018).
breast tumors (1 paper, 2011). "The gene signature associated with high 14-3-3ζ levels in breast tumors encompassed many with functions in mitosis and cytokinesis, including aurora kinase-B, polo-like kinase-1, CDC25B, and BIRC5/survivin." (PMID 21707964, 2011).
Burkitt lymphoma (1 paper, 2019). A rare form of malignant mature B-cell non-Hodgkin lymphoma. "Expression of CDC25B, which is both a MYC target gene in Burkitt lymphoma and necessary for G2/M transition, was decreased upon MB-3 exposure." (PMID 31645904, 2019).
dysplasia (1 paper, 2010). A usually neoplastic transformation of the cell, associated with altered architectural tissue patterns. "CDC25B protein expression increased as tumors progressed; none of the healthy control subjects expressed CDC25B, while one-fourth of the dysplasia subjects and one-half of the patients with invasive cancer expressed CDC25B." (PMID 20813067, 2010).
embryonal carcinoma (1 paper, 2022). A non-seminomatous malignant germ cell tumor characterized by the presence of large germ cells with abundant cytoplasm resembling epithelial cells, geographic necrosis, high mitotic activity, and pseudoglandular and pseudopapillary structures formation. "We found that the PSI value of CDC25B was upregulated and significantly different in embryonal carcinomas, which consistent with the experimental results in NCCIT cells." (PMID 36713456, 2022).
epilepsy (1 paper, 2025). A brain disorder characterized by episodes of abnormally increased neuronal discharge resulting in transient episodes of sensory or motor neurological dysfunction, or psychic dysfunction. "We found that CDC25B, DNMT1, GZMA, MTX1, and SSH2 expression decreases epilepsy risk, whereas FGD3, RAF1, and SH3BP5L increase it." (PMID 39753851, 2025).
female infertility (1 paper, 2013). Diminished or absent ability of a female to achieve conception. "This is not surprising considering that Cdc25B is irreplaceable in oocytes and the absence of Cdc25B, as in Cdc25B null mice, leads to female infertility due to the inability of oocytes to enter M-phase." (PMID 23805152, 2013).
follicular adenoma (1 paper, 2002). "Cdc25B was frequently overexpressed in follicular adenoma and minimally invasive follicular carcinoma, but the incidence was significantly lower in widely invasive follicular carcinoma." (PMID 12085185, 2002). "In particular, follicular adenoma and minimally invasive follicular carcinoma very frequently overexpressed cdc25B, 63.2% (12 of the 19 cases) and 73.1% (19 of the 26 cases), respectively." (PMID 12085185, 2002).
follicular carcinoma (1 paper, 2002). "In papillary carcinoma, 44 of the 72 cases (61.1%) overexpressed cdc25B, indicating that this phenomenon was observed in 74 of the 121 cases (61.2%) of papillary or follicular carcinoma." (PMID 12085185, 2002).
gastric adenocarcinoma (1 paper, 2025). "It is reported that TEAD4 upregulated CDC25B in gastric adenocarcinoma, driving cell aggressiveness and inhibiting sensitivity to cisplatin therapy through cell adhesion." (PMID 40404896, 2025).
glioblastoma (1 paper, 2020). The most malignant astrocytic tumor (WHO grade IV). "CaMKII-mediated inhibitory phosphorylation of cdc25 phosphatases [cdc25B in K562 CML and Jurkat T cell leukemia, and probably cdc25C in glioblastoma cells] prevents the activating dephosphorylation of the cdc25 target p-(Tyr15)-cdc2 as also observed in the present study." (PMID 32390841, 2020).
H1N1 Influenza A (1 paper, 2025). "The degree, closeness, and betweenness values of 3.82, 7.54, and 23.17, respectively, indicated that three major proteins—CDC25B, PARP1, and PTGS2—are involved in the interaction between microbial isolates and H1N1 Influenza A." (PMID 40278270, 2025). "Network pharmacology indicates that CDC25B, PARP1, and PTGS2 are key target proteins involved in the interaction between S. ardesiacus isolates and H1N1 Influenza A." (PMID 40278270, 2025).
HCMV infection (1 paper, 2016). "The identification of IER5 as a target of miR-UL148D and its role in the regulation of CDC25B are also supported by the inverse correlation between IER5 and CDC25B expression that was observed during HCMV infection in host cells." (PMID 27824944, 2016). "According to this model, HCMV infection stimulates IER5 expression, which in turn inhibits CDC25B expression and CDC25B-dependent CDK1 activation, contributing to IE1 transcription and lytic viral replication." (PMID 27824944, 2016). "The failure of CDK1 WT to inhibit IE1 expression at a late stage of HCMV infection likely resulted from the lack of CDC25B activity, correspondingly reducing the activation of CDK1 WT." (PMID 27824944, 2016). "Here, we showed that a HCMV-encoded miRNA, miR-UL148D, robustly accumulates during late stages of experimental latent HCMV infection in host cells and promotes HCMV latency by modulating the immediate early response gene 5 (IER5)-cell division cycle 25B (CDC25B) axis in host cells." (PMID 27824944, 2016).
hypopharyngeal cancers (1 paper, 2022). Carcinoma, predominantly squamous cell, arising from the epithelial cells of the hypopharynx. "Herein, we newly demonstrated that 4 genes (and the proteins) as the most powerful exploratory markers for response prediction to TXT, CDDP, and 5-FU- namely, AGR2, and PDE4D for TXT; NINJ2 and possibly RAB15 for CDDP, and CDC25B for 5-FU- in hypopharyngeal cancers." (PMID 35841085, 2022).
leukemia (1 paper, 2011). A malignant (clonal) hematologic disorder, involving hematopoietic stem cells and characterized by the presence of primitive or atypical myeloid or lymphoid cells in the bone marrow and the blood. "This agent induced a G2/M cell cycle block through a reduction in cell cycle progression signals (FOXM1, KIS, Cdc25B, Cyclin D1, Cyclin A, and Aurora-B), resulting in inhibition of leukemia cell proliferation." (PMID 22132193, 2011). "We found that IER5 expression inhibited the proliferation of both leukemia cell lines and of leukemic blast cells derived from AML through the transcriptional repression of Cdc25B." (PMID 22132193, 2011).
liver cancer (1 paper, 2022). An epithelial or non-epithelial malignant neoplasm that arises from the liver. "The mRNA and protein levels of CDC25B in liver tumors are higher than those in normal tissues, and specific siRNA-targeting CDC25B inhibited liver cancer cell growth in vitro." (PMID 35743699, 2022).
lung squamous cell carcinoma (1 paper, 2025). "The decreased expression level of CDC25B in lung squamous cell carcinoma and prostate adenocarcinoma may also be responsible for this." (PMID 40216745, 2025).
metastasis (1 paper, 2001). The spread or migration of cancer cells from one part of the body (where they first appeared) to another. "CDC25A (+), as well as CDC25B (+), was more frequently found in patients with deeper tumour invasion and lymph node metastasis, while tumour size was correlated only with CDC25A expression." (PMID 11487274, 2001).
multiple myeloma (1 paper, 2021). "Increased CDC25B, AKR1B1, and AKT3 expression was associated with poor multiple myeloma survival, indicating a detrimental effect of certain aging-associated gene patterns." (PMID 34831349, 2021).
myeloid leukemia (1 paper, 2025). A clonal proliferation of myeloid cells and their precursors in the bone marrow, peripheral blood, and spleen. "The authors proposed that IER5 can competitively bind to a Cdc25B promoter transcription factor-binding site in myeloid leukemia cells, thereby releasing transcription factors, such as NF-YB and p300, and inhibiting transcription." (PMID 40852688, 2025).
neuroblastoma (1 paper, 2014). Neuroblastoma (NB) is the most common solid, extracranial childhood tumor. "A majority of FOXM1 target genes, including CDC25B, CHEK2, CENPA, CENPB, and CENPF, were significantly downregulated in neuroblastoma cells with MEIS2 depletion." (PMID 25210800, 2014).
Obesity (1 paper, 2025). Accumulation of substantial excess body fat. "In TNBC tumors of AA patients with obesity, seventeen miRNAs, seven of which (miR-195-5p, miR-130a-3p, miR-130a-5p, miR-424-5p, miR-148a-3p, miR-374-5p, and miR-30a-5p) potentially downregulated two or more genes (e.g., CLCN4, PLCB1, CDC25B, AEBP2, ERBB4)." (PMID 41009685, 2025).
osteosarcoma (1 paper, 2013). A usually aggressive malignant bone-forming mesenchymal neoplasm, predominantly affecting adolescents and young adults. "We have previously found that CDC25B overexpression in the human osteosarcoma cell line U2OS, causes centrosome amplification and that CDC25B associates with centrin 2, an integral component of both mature and assembling centrioles." (PMID 23840880, 2013).
ovarian tumor (1 paper, 2019). "Here, we show that cell division cycle 25B (CDC25B) is over-expressed in ovarian tumors and associated with poor patient prognosis." (PMID 31024841, 2019). "CDC25B expression levels were detected by western blotting in both ovarian tumors and normal ovarian tissue samples from the same patients." (PMID 31024841, 2019). "In this study, we found that CDC25B was over-expressed in ovarian tumors compared with normal ovarian tissues." (PMID 31024841, 2019). "CDC25B was also significantly over-expressed in these ovarian tumor samples compared with normal tissues, p < 0.001." (PMID 31024841, 2019). "CDC25B was over-expressed in ovarian tumors compared with normal ovarian tissues." (PMID 31024841, 2019).
prostate adenocarcinoma (1 paper, 2025). "This discrepancy may arise from the fact that CDC25B overexpression can promote the AF2 domain of the AR to recruit CDC25B, thereby enhancing AR activation in prostate adenocarcinoma." (PMID 40216745, 2025). "Thus, the development and progression of prostate adenocarcinoma are regulated by the complementary and/or synergistic effects of CDC25B overexpression." (PMID 40216745, 2025).
psoriasis (1 paper, 2025). An autoimmune condition characterized by red, well-delineated plaques with silvery scales that are usually on the extensor surfaces and scalp. "This study explores regenerative therapies—exosomes, mesenchymal stem cells (MSCs), epigallocatechin-3-gallate nanoparticles (EGN), and EGN-loaded exosomes (EGN-Exo)—in regulating psoriasis-related markers (IL-6, IL-4, Bcl-2, Bax, NF-κB, CDC25B)." (PMID 40818978, 2025). "This juxtaposition underscores the specificity of molecular targets in different disease contexts, with our research highlighting the therapeutic potential of modulating CDC25B and NF-kB in psoriasis management." (PMID 40818978, 2025). "The present study elucidates the molecular dynamics of psoriasis through the analysis of ELISA results, which revealed elevated expression levels of the CDC25B and NF-kB pathways in affected samples, with values reaching 3.4 and 2.1, respectively." (PMID 40818978, 2025).
Sepsis (1 paper, 2025). Sepsis is defined as life-threatening organ dysfunction caused by a dysregulated host response to infection. "In the GSE65682 sepsis dataset, these genes showed high discriminative ability, with AUC values reaching 0.970 (CDC25B), 0.965 (FBXO31), and 0.967 (PTCD3)." (PMID 41194984, 2025). "Our findings suggest that CDC25B may serve as a central mediator of immune cell differentiation and function in sepsis." (PMID 41194984, 2025). "In conclusion, our study indicates the potential importance of key genes including CDC25B, DPP7, FBXO31, and PTCD3 in the shared pathogenesis of sepsis and T2DM." (PMID 41194984, 2025). "Differential gene expression and co-expression network analyses identified five key genes—CDC25B, DPP7, FBXO31, PTCD3, and CNPY2—that play critical roles in immune response and cellular regulation in sepsis and T2DM." (PMID 41194984, 2025). "Further refinement by intersecting these genes with previously identified DEGs yielded five candidate genes: CDC25B, DPP7, FBXO31, PTCD3, and CNPY2, These genes emerged as promising biomarkers for both T2DM and sepsis, warranting further investigation into their functional roles." (PMID 41194984, 2025).
small bowel tumors (1 paper, 2021). "APC Min mice immunized with CDC25B or COX2 peptides developed fewer small bowel tumors as compared to controls (p=0.01 and p=0.02 respectively)." (PMID 34526999, 2021). "Mice immunized with CDC25B (mean, 53.4 ± 23.5 tumors) or COX2 peptides (50.3 ± 18.1 tumors) developed significantly fewer small bowel tumors as compared to control mice (mean, 87.5 ± 25.7 tumors; p<0.021 for all)." (PMID 34526999, 2021).
thymoma (1 paper, 2021). A neoplasm arising from the epithelial cells of the thymus.
thyroid neoplasms (1 paper, 2002). "The expression status of cdc25B in thyroid tumours differs from that in other carcinomas." (PMID 12085185, 2002). "In summary, this study demonstrated that cdc25B and cdc25A may play an oncogenic role in thyroid neoplasms but may not be directly linked to the cell proliferation of thyroid tumours." (PMID 12085185, 2002). "What is most interesting in this study is the inverse relationship between cdc25B overexpression and the biological aggressiveness of the thyroid tumour, because such an expression status has not been observed in other positive regulators of cell cycle." (PMID 12085185, 2002).
vulvar carcinoma (1 paper, 2010). "Our results suggest that CDC25C and phospho-CDC25C (Ser216) play a crucial role and CDC25B a minor role in the pathogenesis and/or progression of vulvar carcinomas." (PMID 20500813, 2010). "In our study, 16% of the vulvar carcinomas have higher expression of CDC25B than normal vulvar squamous epithelium." (PMID 20500813, 2010). "Our results suggest that CDC25C and phospho-CDC25C (Ser216) play a crucial role and CDC25B a minor role in the development and/or progression of vulvar carcinomas." (PMID 20500813, 2010). "High nuclear CDC25A and CDC25B expression were observed in 51% and 16% of the vulvar carcinomas, respectively, whereas high cytoplasmic CDC25C expression was seen in 63% of the cases." (PMID 20500813, 2010). "However, high phospho-CDC25C (Ser 216) expression was correlated with low expression of CDC25A and high expression of CDC25B, suggesting that the three can collaborate in the tumorigenesis of a subset of vulvar carcinomas." (PMID 20500813, 2010). "Overexpression of CDC25B in 16% of our cases suggests that this protein may contribute to tumorigenesis in a minority of vulvar carcinomas." (PMID 20500813, 2010). "Expression of CDC25A, CDC25B, CDC25C and phosphorylated (phospho)-CDC25C (Ser216) were examined in 300 vulvar carcinomas using immunohistochemistry." (PMID 20500813, 2010). "In the present study, overexpression of CDC25A, CDC25B and CDC25C isoforms was not significant associated with each other, suggesting that overexpression of multiple isoforms in vulvar carcinomas occur through independent pathways." (PMID 20500813, 2010). "Furthermore, no coexpression of CDC25B and phospho-CDC25C (Ser216) was seen in serial sections of vulvar carcinomas." (PMID 20500813, 2010).